ATG7 (autophagy related 7)
Diseases named in the same sentence as ATG7 in open-access papers (continued):
Sharing a sentence is not in itself a finding about the gene and the disease.
cancer (continued). "By decreasing ATG7 expression, Rumex dentatus may disrupt this survival pathway, potentially increasing the vulnerability of cancer cells to apoptosis or other death signals." (PMID 39863836, 2025). "Cytoplasmic FoxO1‐mediated Atg7‐promoted autophagy has been reported in cancer cells." (PMID 38149787, 2024). "The blockade of ATG7-mediated autophagy interrupts IκB degradation by inhibiting cathepsin D, which further activates the NF-κB signaling pathway, which can influence the drug sensitivity of cancer cells." (PMID 38553562, 2024). "ATG7 also plays a role in the resistance of malignant tumors to chemotherapy drugs." (PMID 39464718, 2024). "In addition, the regulation of nuclear factor-kappaB (NF-κB) by ATG7 can also affect drug resistance in cancer cells." (PMID 38553562, 2024). "The indirect methyltransferase inhibitor adenosine dialdehyde decreases Atg7 expression and autophagy in cancer cells, indicating that Atg7-related methylation might be a potential target for treating breast and lung cancer." (PMID 38553562, 2024). "Similarly, the knockdown of ATG7 or Beclin1 or treatment with CQN sensitized cancer cells to epidermal growth factor receptor blocking antibody (Cetuximab) and increased apoptosis." (PMID 37761021, 2023). "In addition, inhibition of the autophagy regulated by autophagy gene autophagy-related 7 (ATG7) can cause the accumulation of damaged mitochondria and reactive oxygen species (ROS), resulting in inhibition of cancer recurrence." (PMID 37014321, 2023). "Similarly, deletion of ATG5 and ATG7 favors the maintenance of an increased level of glycolysis and glycolytic capacity in human cancer cell lines." (PMID 37887330, 2023). "While PIKfyve inhibition elevated MHC-I surface expression in wild-type cells, it did not further increase surface expression of MHC-I in the Atg5-null or Atg7-null cancer cells, confirming that PIKfyve inhibition upregulated MHC-I surface expression by impairing autophagy." (PMID 38011559, 2023). "In addition to the upregulation of the autophagy‐related protein ATG7, we noticed that the early response of cancer cells to HSP90 inhibition induced the accumulation of the adaptor protein p62 or sequestosome‐1." (PMID 35174975, 2022). "Reduced ATG7 expression has prognostic value in several cancers." (PMID 35585060, 2022). "To further determine whether ATG7 exerts its immunosuppressive functions in cancer cells or immune cells, we analyzed the single-cell data from GSE103322." (PMID 36262348, 2022). "However, inhibiting autophagy by deleting the gene ATG5 or ATG7 prevented RAS-mediated cancer cell proliferation." (PMID 35359388, 2022). "In this regard, a study reports the tumor-promoting effect of autophagy in K-Ras [K-Ras(V12)]-induced malignant cell transformation, where inhibiting ROS with antioxidants reduced K-RasV12-induced induction of Atg5 protein and Atg7 protein, autophagy, and cancer growth." (PMID 35359388, 2022). "Many studies investigating the role of autophagy in cancer have involved deletion of Atg7." (PMID 35867735, 2022). "Besides, another study found that inhibition of autophagy by knocking down ATG7 or expressing dominant negative ATG4B in cancer cells resulted in a significant increase in the number of CD8+ T cells infiltrating in pancreatic tumors." (PMID 35600411, 2022). "Note that enhanced levels of ATG7, for instance, have been reported in diverse cancer types and were shown to promote cancer survival and resistance to chemotherapy, whereas a downregulation could counteract cancer development, progression and resistance." (PMID 34944838, 2021). "ATG5, GABARAP, ATG7, and ULK2 had a higher frequency of loss mutations in the pan-cancer analysis." (PMID 34636718, 2021). "Moreover, endogenous noncoding RNA molecules miR‐17 and miR‐137 diminish ATG7 expression, sensitising several cancer cell lines to chemotherapeutics or low ionising radiation." (PMID 34725936, 2021).
cancer (continued). "In humans, the link between ATG7 dysfunction and cancer formation is only starting to emerge." (PMID 34725936, 2021). "In the current study, as in most cases of chemotherapeutic drug treatment, ATRA induced autophagy also played a protective role for the cancer cells, as ATG7 knockdown or CQ treatment both potentiated ATRA induced apoptosis, though overwhelmed by the potency of ATRA." (PMID 33495541, 2021). "Interestingly, ChIP-seq data with NRF1 in 4 different cancer cell lines depicted strong enrichment in close proximity of both ATG7 and ATG5 TSSs." (PMID 34458153, 2021). "We point out a potentially unique role for Atg7, as neither chemical inhibition with Chloroquine nor loss of Beclin-1 or Atg12 induced cancer cell death, even though autophagy signaling was reliably blocked." (PMID 32046105, 2020). "Tang's group demonstrated that knockout or knockdown of autophagy-related 5 (Atg5) and autophagy-related 7 (Atg7) degraded ferritin in fibroblasts and cancer cells, resulting in the limitation of erastin-induced ferroptosis by decreasing intracellular ferrous iron levels and lipid peroxidation." (PMID 32256352, 2020). "Furthermore, autophagy defects induced by the ATG7 knockdown significantly inhibited the degradation of SNAI1 in both cancer cell lines, indicating that ATG7-dependent autophagy is crucial for controlling the protein levels of SNAI1 in cancer cells." (PMID 30736337, 2019). "However, nothing is known about the potential contribution of ATG7 to cancer development at late stages, including cancer progression and invasion." (PMID 31016112, 2019). "An autophagy- and ATG7-independent role of ATG5 in cancer was recently demonstrated." (PMID 31450711, 2019). "When ATG7 was silenced by siRNA transfection to block autophagy, gefitinib-induced inhibition of cell proliferation was potentiated, suggesting that gefitinib-induced autophagy is a survival mechanism of cancer cells." (PMID 30497501, 2018). "Notably, in our hands, autophagy inhibition with HCQ or Atg5/Atg7 RNAi sensitized cancer cells to PPI-induced cell death." (PMID 29789637, 2018). "Furthermore, the Atg7 protein was highly activated after the mTOR/p70S6K signaling pathway was triggered in DBT-treated cancer cells." (PMID 29179457, 2017). "Specifically, Cas9 knockout of ATG3/ATG7, could disrupt autophagy flux and sensitize the cancer cells to etoposide." (PMID 28981103, 2017). "Furthermore, recently many reports have shown that suppression of autophagy by silencing ATG7 and beclin 1 results in increase in ROS generation leading to sensitization of cancer cells to drug induced apoptosis." (PMID 24755562, 2014). "Thus, ATG7 is of significant importance in both cancer progression and treatment responses." (PMID 39863836, 2025). "Therefore, it is reasonable to believe that cancer cells may also have a regulatory effect on the expression of ATG7 in fibroblasts." (PMID 40707430, 2025). "The link between ATG7 and the Warburg effect could provide new strategies for cancer treatment." (PMID 38553562, 2024). "Thus, ATG7 plays a significant role in cancer resistance to chemotherapy drugs." (PMID 39464718, 2024). "Interestingly, ATG7 seemed to function in myeloid cells instead of cancer cells in TIME." (PMID 36262348, 2022). "However, whether the reduced ATG7 expression level in these cancer types is the result of alteration in the alternative-splicing machinery or another process remains to be explored; rescue of the defect by expression of wild-type ATG7 would be informative." (PMID 35585060, 2022). "Another important remaining question from this work is whether hemizygosity (or nonfunctional heterozygosity) of Atg7 and the phenotypes associated with this genotype are relevant to human cancer." (PMID 35867735, 2022). "Indeed, miR-582-5p-mediated suppression of ATG7 could inhibit autophagy, indicating the UCA1/miR-582-5p/ATG7 pathway regulates BC anti-cancer drug response." (PMID 32756406, 2020).
cancer (continued). "However, the PARP cleavage occurred earlier to 3 h, if autophagy essential gene atg7 has been deleted in these cells, indicating that the cellular protective mechanism autophagy is also triggered by NiPT when it kills cancer cells in the meantime." (PMID 32292717, 2020). "BRAF mutants with Atg7 deletion tend to live longer as opposed to mice with KRAS mutation that die from pneumonia instead of cancer suggesting that autophagy deficiency might promote inflammation." (PMID 29643976, 2018). "Further, elevated expression of key autophagy proteins beclin-1, ATG-7, LC-3-I/II, and SQSTM1/p62 reveal that inhibition of autophagy plays a crucial role in regulating DDR capabilities of cancer cells." (PMID 40041432, 2025). "Pterostilbene restores autophagic activity in cisplatin-resistant OSCC cells by activating autophagy-related genes, including ATG5, ATG7, and Beclin-1, through modulation of the AKT pathway, leading to enhanced cancer cell death." (PMID 39840028, 2024). "In a study of therapeutics targeting cancers, mTOR activation triggered CREB1 phosphorylation and accumulation, and inhibiting CREB1 led to a decrease in ATG7, which is a key factor in autophagy regulation." (PMID 37947633, 2023). "SIRT-1, which is typically localized to the nucleus in cancer cells, forms a molecular complex with three proteins essential for autophagy initiation: ATG-5, ATG-7, and LC3." (PMID 37850626, 2023). "Knockout or knockdown of ATG7 and ATG5 upregulated ferritin expression, decreased Fe2+ levels, and limited erastin-induced ferroptosis in fibroblasts and cancer cells." (PMID 37522124, 2023). "In the present study, we investigated the role of cancer cells in the autophagy of SCs by upregulating ATG7 expression, which is mediated by neurotrophic factors, such as NGF, secreted by cancer cells." (PMID 35109895, 2022). "To date, many related pathways have been found to mediate ferroptosis in cancer cells, including system Xc-/GSH/GPX4, FSP1/CoQ10/NAD(P)H, and ATG5/ATG7/NCOA4 pathways, which are considered potential therapeutic targets, especially for the treatment of cancers." (PMID 36009223, 2022). "Specifically, ATG9B was a protective factor in HNSCC patients through downregulating cancer cell EMT, and ATG7 was correlated with the immunosuppressive environment in HNSCC." (PMID 36262348, 2022). "To date, there are at least three pathways that mediate ferroptosis in cancer cells: system Xc-/GSH/GPX4, FSP1/CoQ10/NAD(P)H, and ATG5/ATG7/NCOA4." (PMID 36009223, 2022). "Mechanistically, genetic or pharmacological inhibition of SRMS induced cancer cell senescence in an ATG5- and ATG7-dependent manner." (PMID 34077419, 2021). "Fusobacterium nucleatum promotes cancer by upregulating ULK1 and ATG7 to induce resistance to oxaliplatin and 5-fluorouracil (5-FU) in colorectal cancer (CRC)." (PMID 34895252, 2021). "For other cancers, studies have shown that F. nucleatum regulates the expression of endogenous LC3 and ATG7 and the formation of autophagosomes, resulting in chemoresistance to 5-FU, cisplatin (CDDP), and docetaxel." (PMID 34895252, 2021). "Taken together, the current data demonstrate that ceRNAs can participate in many steps of autophagy by upregulating some key molecules, such as ULK1, ATG3, ATG7, and ATG4, resulting in chemoresistance in various cancers." (PMID 33050642, 2020). "HOTAIRM1 functions as a ceRNA to regulate autophagy initiation and elongation through ULK1, ATG3, ATG7, and ATG12 in cancers." (PMID 33050642, 2020). "In order to verify if the anti-cancer effect of SRT2183 is dependent on the autophagy, we knocked down autophagy related 5 (ATG5) and autophagy related 7 (ATG7), two master regulators of autophagy, by shRNA-lentivirus." (PMID 33223507, 2020). "To investigate how the knockdown of the ATG7 gene affects SNAI1 degradation, we transiently transfected plasmids containing ATG7 shRNA and control shRNA into two cancer cell lines (HeLa and H1299) and incubated the cells for 24 h." (PMID 30736337, 2019).
cancer (continued). "Recently, some inhibitors of ATG7 (WO2018/089786) have been designed and it has extended the use of micro RNAs that target ATG7 gene such as miR-154 that inhibits blade cancer progression." (PMID 31635099, 2019). "Depletion of AMPK or autophagy-related protein 7 (ATG7) inhibited the upregulation of autophagy in response to TTFields, as well as sensitized cells to the treatment, suggesting that cancer cells utilize autophagy as a resistance mechanism to TTFields." (PMID 30341282, 2018). "Increased expression of the autophagy-related proteins Atg5, Atg7, Atg12, p62, and LC3 enhanced autophagy, which would degrade inadequate protein aggregates and also provide nutrients for rapidly growing cancer cells." (PMID 28358375, 2017). "Inhibition of LSD1 with either siRNA or the LSD1 inhibitor SP2509 stimulated expression levels of the autophagy markers ATG7 and LC3-II in different cancer cells." (PMID 29088798, 2017). "In our study, miR-375 was significantly lower, atg7 and autophagy (indicated by LC3II/I conversion rate) were activated in CRC carcinoma tissues." (PMID 28186962, 2017). "In our experimental conditions, autophagy played a pro-survival role in cancer cells treated with HMA, given that cell viability decreased, although only partially, when the crucial autophagy regulators Beclin-1 or ATG7 were silenced." (PMID 27816051, 2016). "Furthermore, circATG7 was found to facilitate autophagy and promote cancer progression through the miR-766-5p/ATG7 and HUR/ATG7 axes." (PMID 41301888, 2025). "The findingsdemonstrated that ATG-7 siRNA might inhibit cells’ capacityto activate autophagy by silencing ATG-7 gene, hence reducing thesurvival of human MCF-7 cancer cells after chemotherapy." (PMID 38973850, 2024). "Similarly, pterostilbene restores autophagic activity in cisplatin-resistant OSCC cells by activating autophagy-related genes, including ATG5, ATG7, and Beclin-1, through modulation of the AKT pathway, leading to enhanced cancer cell death." (PMID 39840028, 2024). "In vivo, the mice in the model groups displayed cancer progression, and the expression of some of the autophagy-related genes, DRAM1, NBR1, ATG7, MAP1LC3A were also increased in mice given F. nucleatum or F. nucleatum with L-cysteine when compared to the untreated control mice." (PMID 37889013, 2023). "Silencing the autophagy genes, such as ATG5, ATG7, and BECN1, could inhibit the DAMP release from mitoxantrone or oxaliplatin-treated cancer cells and subsequently impair the antitumor immunity." (PMID 36814780, 2023). "In ICD-suffering cancer cells, upon knocking down Beclin-1, ATG5 or ATG7 could reduce the ATP release and consequently inhibit anticancer immunity in vivo." (PMID 36814780, 2023). "Hydrogen peroxide (H2O2) and 2–methoxyestradiol (2–ME) induced autophagic cell death in various cancer cells, which was inhibited by 3–MA or the deletion of Beclin–1 or Atg7 but not by pan caspase inhibitor Z–VAD." (PMID 37762548, 2023). "The genes ITGA3, HSPA8, CTSD, ATG12, CLN3, ATG7, and MAP1LC3C negatively influenced patient survival, whereas WIPI1 may protect the patients from cancer-related death." (PMID 35186475, 2022). "Further single-cell analysis and multiple immunofluorescence colocalization analyses indicated that ATG7 contributed to the high expression of PD-L1 in myeloid cells but not cancer cells." (PMID 36262348, 2022). "Previous studies showed that Sirt1 might regulate autophagy due to deacetylation of Atg5, Atg7, or LC3 in cancer cells, MEFs, germ cells, and stem cells." (PMID 33723227, 2021). "Although aberrant ATG7 activity is not known to commonly underpin human cancers, it has been theorised that disrupting autophagy can improve the potency of anti‐cancer therapeutics." (PMID 34725936, 2021).
cancer (continued). "Moreover, a prodigious body of evidence supports a role for ATG7 in protecting against complex disease states in model organisms, although how dysfunctional ATG7 contributes to manifestation of these diseases, including cancer, neurodegeneration and infection, in humans remains unclear." (PMID 34725936, 2021). "For example, initially during early tumorigenesis, BRAF-driven lung tumor formation was accelerated upon Atg7 deletion, but later, these tumors slowed their growth and failed to transition from benign to malignant tumors." (PMID 34298710, 2021). "The critical role of autophagy in K-ras-driven cancers is further confirmed by a synthetic lethal screening for factors that support K-ras addiction, which identified Atg7 and RAF kinases as a minimal oncoeffector combination that best discriminates K-ras cancer cells from normal cells." (PMID 32807225, 2020). "In inducible Atg7-knockout mice, the growth of KRAS-driven lung tumors was significantly inhibited before any signs of neurotoxicity, indicating that therapeutic window for autophagy inhibition exists in some cancers." (PMID 32641008, 2020). "Literatures showed that targeting autophagy-related proteins LC3, ATG5, ATG7, SQSTM1, and Akt/mTOR (mammalian target of rapamycin) pathway could regulate autophagy initiation in cancer cells." (PMID 31309361, 2019). "Although ATG7‐dependent autophagy has been reported in a variety of cancers, its involvement in human BC invasion has never been explored." (PMID 31016112, 2019). "Although often presumed to be caused by its degradative feature, we demonstrated in irradiated cancer cells that knockdown of ATG7 or LC3B, but not treatment with lysosomal inhibitor chloroquine, sensitizes cancer cells to radiation." (PMID 27933272, 2016). "However, the cytotoxicity of BRAF and CRAF siRNAs is enhanced when ATG7 is knocked down, suggesting that KRAS-driven metabolic alterations in cancer cells make them particularly dependent on the autophagy pathway as a survival mechanism when the RAF/MAPK pathway is acutely inhibited." (PMID 39272847, 2024). "Further, HSF1 involves multiple layers of cellular regulations to promote malignant phenotypes in cancer cells, including increasing glycolysis to overcome therapy resistance via lactate dehydrogenase A (LDH-A) and promoting autophagy to enhance cell survival via autophagy-related protein 7 (ATG7)." (PMID 37958341, 2023). "Consequently, many ATG7 suppressors (e.g., WO2018/089786) have been developed, extending the use of micro RNAs (miRNAs) targeting the ATG7 gene, including miR-154, which suppresses blade cancer growth." (PMID 36766800, 2023). "Similarly, the glycolysis inhibitors 3-BrPA, 2-DG, lonidamine and DCA demonstrate greater cytotoxicity in ATG7 or ATG5 knockdown cancer cell lines than in the corresponding wild-type cell lines, as was evidenced by decreased viability and proliferation and increased cell death." (PMID 37887330, 2023). "Indeed, recent studies in skeletal muscle and cancer cells reported that pharmacological activation of REV-ERBα inhibits autophagosome formation via negative modulation of core autophagy genes such as Ulk3, Ulk1, Bec1, Atg7, and Atg5." (PMID 35428762, 2022). "In KRAS-driven cancers, Atg7 depletion did not affect the antiproliferative effect of CQ, suggesting that the antitumor effect of CQ might be independent of autophagy." (PMID 34844627, 2021). "Additionally, BIRC5 negatively modulates the protein stability of ATG7 and physically binds to the ATG12–ATG5 conjugate, thereby preventing formation of the ATG12–ATG5–ATG16L1 protein complex in human cancer and suggesting that BIRC5 can directly regulate autophagy in cancer cells." (PMID 33109128, 2020).